CD9 (CD9 molecule)
Diseases named in the same sentence as CD9 in open-access papers (continued):
Sharing a sentence is not in itself a finding about the gene and the disease.
prostate carcinoma (42 papers, 2007 to 2025). A carcinoma that arises from epithelial cells of the prostate gland. "The effects of IGSF8 appear to be mediated through its interaction with a tetraspanin protein, CD9, previously implicated in prostate cancer progression." (PMID 26036626, 2015). "Our results showed that CD9 interactions with mortalin are linked to cell death through mitotic catastrophe in prostate cancer cells, showing the importance of CD9 in tumour suppression." (PMID 17848953, 2007). "Consequently, CD9 has the potential to serve as a routine immunohistochemical biomarker for diagnosing and stratifying the risk of prostate cancer." (PMID 40860827, 2025). "High levels of CD9 evaluated with this antibody were associated with poor prognosis in gastric cancer, while the association with good prognosis was found for mesothelioma, cervical and prostate cancer." (PMID 37007105, 2023). "Little is known about the cause of CD9 dysregulation in prostate cancer, however there are several miRNA-binding sites in the 3 ́UTR of the transcript suggesting it could be post-transcriptionally regulated." (PMID 29416746, 2018). "Loss of CD9 expression correlates with poor prognosis in bladder carcinoma and esophageal squamous cell carcinoma, small and non-small cell lung cancers and prostatic carcinoma." (PMID 23128478, 2013). "The CD9-positive EVs were higher in patients with prostate cancer compared to ones with benign prostate hyperplasia, and its secretion can be modulated in response to dihydrotestosterone." (PMID 37007105, 2023). "For example, when investigating prostate cancer, exosomal proteins including CD9, CD81, P-glycoprotein, and ACTN4 together can act as a detection panel with high specificity." (PMID 35757760, 2022). "Very recently, we found that in peripheral blood from prostate cancer (PCa) patients, NK cells show enhanced CD9, CD49a and CXCR4 expression." (PMID 34638439, 2021). "We demonstrated that DHT increases the abundance of CD9 in the isolated total S‐EVs from prostate cancer cells." (PMID 34434533, 2021). "We recently provided evidence that miR-518f-5p decreased the expression of the tetraspanin CD9 in prostate cancer cells, suggesting a key regulatory role of this miRNA on the function of this tetraspanin in tumor progression and invasive capacity." (PMID 32224917, 2020). "miR-518f-5p has been shown to modulate the expression of the metastasis suppressor CD9 in prostate cancer." (PMID 32224917, 2020). "We were the first to provide evidence of a role for miR-518f-5p in modulating CD9 protein expression and migration in prostate cancer cells, thus implicating miRNAs in the regulation of CD9 in cancer." (PMID 32224917, 2020). "CD9 is considered a metastasis suppressor, typically exhibiting low protein levels in advanced prostate cancer and metastasis, leading to poor patient prognosis." (PMID 32224917, 2020). "In contrast, CD9 knockout mice crossed onto the TRAMP prostate cancer mouse model led to a significant decrease in spontaneous metastasis to the liver, thereby implicating CD9 in prostate cancer progression and metastasis." (PMID 29416746, 2018). "In prostate cancer, the altered expression of the tetraspanins CD9 and CD151 is commonly seen as a tumour progresses towards a metastatic phenotype." (PMID 29891991, 2018). "In contrast to what is typically observed in prostate cancer, LNCaP cells, which are derived from a lymph node metastasis of prostate cancer, had high levels of CD9 mRNA, CD9 total and cell surface protein." (PMID 29416746, 2018). "The aggressive DU145 and PC3 prostate cancer cells displayed reduced luciferase activity with the CD9 3’UTR compared to RWPE1 control, which is indicative of endogenous regulatory factors acting within these cells to repress CD9 levels." (PMID 29416746, 2018). "This study aimed to investigate the influence of miRNA on CD9 levels and determine if miRNAs are responsible for decreased CD9 protein levels in prostate cancers." (PMID 29416746, 2018).
prostate carcinoma (continued). "Typically, when prostate cancers become more aggressive and progress towards a metastatic phenotype, they experience alterations in tetraspanin expression, where CD9 levels decrease and CD151 levels increase." (PMID 29891991, 2018). "In this study, we have shown that CD9+ halos surround lymphatic vessels in human prostate cancer specimens and that EEV fractions promoted the migration of CX3CR1+ human PC3-ML prostate cancer cells in a CX3CL1-dependent manner." (PMID 29650776, 2018). "The discrepancy between these two studies warrants further investigation of CD9 in prostate cancer to clarify if CD9 acts as a metastasis suppressor." (PMID 29416746, 2018). "CD9 is an upstream regulator of AR, and exosomes can deliver CD9 to modulate paracrine signaling to mediate the growth of androgen deprived prostate cancer." (PMID 29228644, 2017). "We also found that the content of CD9 positive EV in plasma of prostate cancer patients was higher than for BPH patients, warranting further analysis in larger patient cohorts to validate plasma derived CD9 positive EV as potential prostate cancer biomarkers." (PMID 28881726, 2017). "We conclude that CD9 positive EV are involved in mediating paracrine signalling and contributing toward prostate cancer progression." (PMID 28881726, 2017). "The EV marker CD9 is highly expressed in colorectal, breast, endometrial, and prostate cancer and it has often been used as a common marker of exosomes in the past." (PMID 28881726, 2017). "Urothelial AGR2 expression was 40 times lower than prostate cancer AGR2 expression as calculated from the array signal intensity values for AGR2 in CD9+ urothelial cells and sorted CD26+ prostate cancer cells." (PMID 26894971, 2016). "Of note is the presence of several well-known exosomal proteins within the top echelon (i.e. CD9, TSG101, Alix/PDCD6IP) and interestingly, CD9 was increased in prostate cancer samples." (PMID 26196085, 2015). "Several tetraspanins such as CD81, CD9, tetraspanin-6 and tetraspanin-8 were enriched in prostate cancer versus control samples." (PMID 26196085, 2015). "Another study conducted on prostate carcinoma progression noted a significant increase in CD9 expression in primary, metastasizing adenocarcinoma compared to advanced, non-metastasizing adenocarcinomas." (PMID 23840773, 2013). "Two prostate cancer cell lines were maintained in culture, as a source of PCa-exosomes, and the expression of typical exosome-markers (e.g. the tetraspanin CD9) and some known markers of prostate (PSA and PSMA) were examined." (PMID 19138409, 2009). "We further show that introduction and overexpression of wild-type CD9 into human PC-3 prostate cancer cells induces mitotic catastrophe." (PMID 17848953, 2007). "Using co-immunoprecipitation and mass-spectrometric protein sequencing, we have identified in prostate cancer cells, a novel CD9 partner, the 75-kDa protein HSPA9B, also known as mortalin." (PMID 17848953, 2007). "Converse immunoprecipitation with anti-mortalin antibody revealed CD9 on immunoblot, confirming their interaction in prostate cancer cells." (PMID 17848953, 2007). "Using converse co-immunoprecipitation, we confirmed that mortalin is a new CD9 partner in prostate cancer cells." (PMID 17848953, 2007). "Our recent studies have shown that CD9 expression is also significantly reduced and even lost during prostate cancer progression." (PMID 17848953, 2007). "In order to characterise such partners in prostate cancer cells, we used mass-spectrometric analysis to identify proteins that co-immunoprecipitated with CD9." (PMID 17848953, 2007). "We show that overexpression of CD9 in human PC-3 prostate cancer cells is sufficient to induce mitotic catastrophe, which is also known as mitotic cell death." (PMID 17848953, 2007).
prostate carcinoma (continued). "Researchers have found that knocking out transmembrane tetraprotein CD9 in the Transgenic Adenocarcinoma of Mouse Prostate (TRAMP) model of newly diagnosed prostate cancer increases spontaneous metastasis in an organ specific manner (i.e., increases liver metastasis rather than lung metastasis)." (PMID 40860827, 2025). "EVs from individuals with prostate cancer typically include cancer-related proteins such as CD9, CD81, and TSG101, as well as Annexin A2, Fatty Acid Synthase (FASN), and a prostate cancer-specific biomarker termed FOLH1 (Prostate Specific Membrane Antigen or PSMA)." (PMID 36059497, 2022). "However, CD63 and CD9 expression in the tissue of prostate cancer and benign hyperplasia is still poorly understood." (PMID 35204378, 2022). "Moreover, a higher expression of exosomal CD9 in plasma from prostate cancer patients had also been revealed in another study by differential centrifugation." (PMID 35757760, 2022). "Nevertheless, they investigated the role of CD9 in prostate cancer and found that exosomal CD9 could promote cancer cell proliferation." (PMID 35757760, 2022). "Interestingly, DHT treatment leads to increased cell surface area and the appearance of filopodia on the cell surface and expression of EV markers CD63 and CD9 on the cell surface of prostate cancer cells." (PMID 34434533, 2021). "Hence, we further investigated if PSMA- as well as CD9-targeted specific isolation of prostate cancer-derived EVs is feasible using immunomagnetic beads." (PMID 34079007, 2021). "Manipulation of the AR signalling axis alters the protein cargo in S‐EVs in LNCaP prostate cancer cells, and that the tetraspanin CD9 has been shown to be significantly more abundant in EVs from DHT‐treated cells when comparison with other S‐EVs markers including: TSG101, Alix, CD63 and CD81." (PMID 34434533, 2021). "Because it had a direct association with several exosome markers, such as CD9, CD81 and CD82, we carried out exosome extraction and analysis for the prostate cancer cell lines PC3 and Du145 cells with EWI‐2 CRISPR/Cas9 knockout as well as the overexpression of EWI‐2 in PC3 cells." (PMID 33605506, 2021). "In accordance with this hypothesis we identified miR-518f-5p as a regulator of CD9 and evaluated the functional relevance of this miRNA to prostate cancer progression in vitro." (PMID 29416746, 2018). "Given that CD9 levels and miRNAs are typically altered in prostate cancer, we hypothesized that CD9 may be regulated by miRNAs in prostate cancer, and this may contribute to cancer progression." (PMID 29416746, 2018). "Moreover CD9 positive EV were also found to be significantly higher in plasma from prostate cancer patients in comparison with benign prostatic hyperplasia patients." (PMID 28881726, 2017). "For example, the expression of CD9 significantly decreased in metastatic breast cancer, colonic cancer and prostate cancer cells than in primary tumor cells, while the high expression of CD9 could weaken migration ability of various kinds of tumor cells." (PMID 24788635, 2014). "We hypothesised that differential expression or distribution of such partners could be responsible for the striking differences observed following CD9 overexpression in the different human prostate cancer cell lines." (PMID 17848953, 2007). "Our results not only identified mortalin as a new CD9 partner, but also clarify the mechanisms by which CD9 may control prostate cancer progression." (PMID 17848953, 2007). "Similarly, miR-518f-5p can reduce the expression of the tetraspanin CD9 in prostate cancer cells." (PMID 37189131, 2023). "However, regulation of CD9 in prostate cancer cells remains to be fully elucidated." (PMID 29416746, 2018). "Therefore, the results from this study suggest that miR-518f-5p may play an important role in prostate cancer progression via modulation of migration and adhesion through regulation of CD9 expression and potentially a range of other cancer related proteins." (PMID 29416746, 2018).
prostate carcinoma (continued). "In this study, we have characterised the role of androgens specifically DHT, in regulating EV secretion from prostate cancer cells and demonstrate that CD9-enriched EV can modulate cellular proliferation when the availability of androgen is limited as may occur during androgen deprivation therapy." (PMID 28881726, 2017). "Moreover, the novel CD9 fusion genes in prostate cancer lack the IGSF8 binding epitope." (PMID 26036626, 2015). "The aim of the current study was to analyze CD63, CD9, and MMR protein expression in prostate tissue in patients with prostate cancer and benign hyperplasia and its correlation with ISUP grade groups and progression-free survival." (PMID 35204378, 2022). "Previous studies have shown the value of exosomal CD9 and CD63 for the prostate cancer diagnostics in blood and urine." (PMID 35204378, 2022). "While the expression and subcellular localisation of tetraspanin EV markers CD9 and CD63 are distinct in prostate cancer, the effect of androgens such as DHT and ENZ on the S‐EVs profile is unclear." (PMID 34434533, 2021). "Whilst there was little variation in CD9 mRNA levels, more aggressive prostate cancer cell lines (DU145 and PC3) displayed the highest levels of CD9 mRNA." (PMID 29416746, 2018). "Moreover, CD9 may be involved in different pathways associated with migration in non-tumorigenic prostate cells compared to prostate cancer cells." (PMID 29416746, 2018). "EVs are enriched in tetraspanins, two of which (CD9 and CD151) have altered expression patterns in many solid tumours, including prostate cancer, as they advance toward metastasis." (PMID 29891991, 2018). "As miR-518f-5p and miR-4289 showed the greatest capacity to regulate the CD9 3’UTR, their ability to alter CD9 levels in prostate cancer cells and the resultant change in cell function was investigated." (PMID 29416746, 2018). "In urine, the level of CD9 positive and CD63 positive EV have been shown to be higher in men with prostate cancer, as well as in plasma, supporting the clinical utility of CD9 positive EV measurement in patients biofluids for men with prostate cancer." (PMID 28881726, 2017). "We further investigated the differences on EV markers CD9, TSG101 and Alix in prostate cancer cell lines and in prostate tissue." (PMID 28881726, 2017). "We evaluated this assay system with exosomes isolated from culture supernatants of prostate cancer cell line PC3 using anti-CD63 antibody and anti-CD9 antibody." (PMID 26082068, 2012). "Anti-CD9 and anti-PSMA functionalized antibodies magnetic beads were used to isolate sEVs from prostate cancer cell lines (LNCaP and PC-3), blood plasma of healthy volunteers and prostate cancer patients." (PMID 37504087, 2023). "To investigate whether EVs derived from communicating prostate cells allow for reliable conclusions on prostate cancer development, we isolated PSMA-positive, as well as CD9-positive, EVs from cell-free urine with the use of magnetic beads." (PMID 35740652, 2022). "Based on this observation and assumption, we further extracted the exosomes from the cell culture medium of prostate cancer cells, performed western blot analysis and confirmed their identity using positive exosome markers (Annexin, EpCam, CD54, CD9 and flotillin)." (PMID 33605506, 2021). "Interestingly, some EV markers such as ALIX were expressed to a lesser extent in prostate cancer-derived cell lines and EVs when compared to TSG101 or CD9." (PMID 34079007, 2021). "Likewise, CD9 was present with the strongest signals within the overall analyzed EV proteins and increasing signals from the healthy control PNT1A to the prostate cancer cell lines 22Rv1, LNCaP to PC3." (PMID 34079007, 2021). "A theranostic antibody designed to specifically detect PSMA helps to further differentiate between circulating S‐EVs from prostate cancer patients, for both CD9 and CD63 captured S‐EVs, providing enhanced potential to assess heterogeneity of S‐EVs for prostate cancer diagnosis." (PMID 34434533, 2021).
prostate carcinoma (continued). "CD9 mRNA modifications involving deletions or missense mutations have been found in a small percentage of prostate cancer patients and some prostate cancer cell lines, with CD9 protein not detected in the majority of these cases." (PMID 29416746, 2018). "In contrast, the aggressive prostate cancer cells had the lowest levels of CD9 cell surface protein and total CD9 protein levels compared to non-tumorigenic RWPE1 cells." (PMID 29416746, 2018). "In this study, CD9 mRNA and protein levels were found to be similar in non-tumorigenic and prostate cancer cell lines." (PMID 29416746, 2018). "Effects on adhesion and migration were not unexpected in the context of CD9, as a previous study showed effects on metastasis in vivo, however alterations to proliferation have not been reported in normal prostate or prostate cancers." (PMID 29416746, 2018). "To assess whether CD9 EV can serve as biomarker in prostate cancer, we examined the level of CD9 positive and CD63 positive EV in prostate cancer in plasma derived from prostate cancer patients (n=6) and benign prostate hyperplasia (BPH) patients (n=10)." (PMID 28881726, 2017). "Our study has confirmed that DHT can increase the secretion of CD9 positive EV and DHT alters EV content and that CD9 positive EV measurement in patients’ blood based-biofluids may provide alternative biomarkers for prostate cancer patients." (PMID 28881726, 2017). "The outcome of these studies demonstrate that CD9 positive EV can mediate paracrine signalling in prostate cancer proliferation in the absence of androgens and that CD9 positive EV are a potential candidate as a prostate cancer biomarker." (PMID 28881726, 2017). "Treatment with CD9 enriched EV was able to increase the cellular proliferation of androgen-deprived LNCaP cells independently of DHT, thereby demonstrating a role of CD9 through EV in prostate cancer cell proliferation." (PMID 28881726, 2017). "In prostate cancer, CD9 has been identified as a candidate gene involved in androgen-deprived cell proliferation through its interaction with IGSF8, suggesting a role of CD9 itself in AR-mediated prostate cancer progression." (PMID 28881726, 2017). "The exosomal (CD9- CD81-SCARB2) (average enrichment 2.40) and lysosomal (CTSD- LAMP2- CTSZ- SPNS1- PSAP) (average enrichment 4.15) proteins were also enriched in exosomes from prostate cancer patients." (PMID 26196085, 2015). "Moreover, ExoScreen allowed sensitive detection of exosomes in human serum from healthy donors and prostate cancer patients using anti-CD63 antibody and anti-CD9 antibody." (PMID 26082068, 2012). "We had already demonstrated that as compared to BPH, the CD9 protein is expressed at lower level in human prostate cancer cell lines (data not shown)." (PMID 17848953, 2007). "This may be important with respect to CD9 functions as Cd9−/− transgenic adenocarcinoma mouse prostate (TRAMP) prostate cancer mice displayed increased liver metastases, but no changes to lung metastases." (PMID 32224917, 2020). "However, this requires an understanding of the mechanism/s by which CD9 expression and function is regulated in non-tumourigenic prostate and prostate cancer cells, which we have partially addressed with this study." (PMID 29416746, 2018). "However, this was not the case for CD9 mRNA and total protein levels, with non-tumorigenic cells having similar levels to prostate cancer cell lines." (PMID 29416746, 2018). "However, most prostate cancer cells had decreased CD9 cell surface levels compared to non-tumorigenic prostate cells." (PMID 29416746, 2018). "Moreover, exogenous CD9 expression does not significantly affect the growth and the invasive properties of a highly metastatic prostate cancer cell line." (PMID 17848953, 2007).